BDNF (brain derived neurotrophic factor)
Diseases named in the same sentence as BDNF in open-access papers (continued):
Sharing a sentence is not in itself a finding about the gene and the disease.
depression (continued). "Abnormalities in BDNF, glutamate receptors, VEGF signaling, and long-term potentiation (LTP) pathways also contribute to the pathophysiological progression of depression by affecting neuroplasticity and neurogenesis." (PMID 37063278, 2023). "The use of etomidate upregulates the expression of BDNF, Nrf2 and GPX4, thereby inhibiting ferroptosis in hippocampal neurons and improving depression-like states in rats." (PMID 38259274, 2023). "Although the BDNF-MAPK-CREB pathway plays a key role in the pathophysiology and treatment of depression, the molecular mechanisms through which GC induces adaptive changes in this signaling cascade are not fully understood." (PMID 36818650, 2023). "The release of BDNF from platelets may be impaired in depressed patients, whereas antidepressants increase the release of BDNF from platelets, suggesting that BDNF from platelets is a factor contributing to the interaction between peripheral BDNF levels and depression." (PMID 36831706, 2023). "BDNF, NPY, and TNF have been reported to be involved in the regulation of depression mediated by ELS, showing sex differences, too." (PMID 35663561, 2022). "Several brain regions involved in depression are shared with CSS, and BDNF exerts a complex role in the physiopathology of these conditions." (PMID 35344113, 2022). "Despite the limitations of the study, current findings provide additional elements regarding the major role of BDNF and especially the mBDNF isoform in the clinical response to ECT in major depression." (PMID 35203890, 2022). "However, studies show that the changes in BDNF following successful treatment are more evident in MDD than in bipolar depression." (PMID 35448545, 2022). "In a recent report, paeoniflorin can improve the depression-like behavior of PSD model mice and increase the expression of BDNF and phosphorylated CREB in the CA1 region of the hippocampus." (PMID 36408279, 2022). "Together, these findings suggest that the basal BDNF/trkB signaling is weaker in the HC and PFC of rats that are prone to developing a stress-induced depression-like phenotype as compared to depression-resilient rats." (PMID 36499323, 2022). "In conclusion, metformin's potential antidepressant impact suggests that inflammation and oxidative stress play a role in depression via various signaling molecules and pathways, including Nrf2, pro-inflammatory cytokines, and the AMPK/BDNF and NFκB pathways." (PMID 36185927, 2022). "This review summarizes the pharmacological regulations of natural products from TCM in the prevention and treatment of depression from the aspects of transcription factors (CREB, NF-κB, Nrf2) and molecular signaling pathways (BDNF-TrkB, MAPK, GSK-3β, TLR-4)." (PMID 35923544, 2022). "However, there are still no data on the association of diagnosed depression with a decrease in the levels of brain BDNF, which may reflect a lesser extent of possible changes in the levels of BDNF in depression compared with AD." (PMID 35563389, 2022). "Noradrenaline also has impact on neuroplasticity via brain‐derived neurotrophic factor (BDNF), which is key for prefrontal and hippocampus neurons playing a role in depression." (PMID 35846210, 2022). "One example is a brain-derived neurotrophic factor (BDNF), a growth factor shown to be lowered in depression, and BDNF can be used as a biomarker for neuropsychiatric illness." (PMID 36075922, 2022). "Additionally, the correlation between LOX activity and BDNF levels leads to hypothesize that huauzontle contains components, released by fermentation, which may participate in the intestine-brain axis to reduce symptoms of depression and anxiety." (PMID 36613269, 2022).
depression (continued). "Antidepressant treatment of CUMS mice revealed that changes in the levels of miR-34a-5p, miR-126, miR-200a-3p, and miR-144-3p influenced the BDNF–ERK/Akt signalling pathway and participated in the development of depression." (PMID 35562946, 2022). "A previous study found that LPS-induced depression-like behaviour in mice by decreasing CREB and BDNF expressions in the prefrontal cortex (PFC) and hippocampus." (PMID 36362262, 2022). "For example, quercetin attenuates LPS-induced depression-like behavior and learning memory impairment in rats, which may be related to its modulation in the imbalance of hippocampal Copine 6 and TREM1/2 expression associated with brain-derived neurotrophic factor." (PMID 35369029, 2022). "Brain-Derived Neurotrophic Factor (BDNF), altered in the brain both of subjects with depression and obesity, provides a potential link between depression and thrombosis." (PMID 35911513, 2022). "We screened for depression using EPDS and MADRS, investigated several psychosocial variables, and took blood samples for BDNF val66met genotyping, epigenetic, and protein analysis." (PMID 34989854, 2022). "Before treatment, the serum levels of BDNF and NGF in patients with depression were 68.18 ± 16.37 (ng/mL) and 75.44 ± 18.59 (ng/mL), respectively." (PMID 35069013, 2022). "BDNF’s dysregulation and depletion, particularly in the hippocampus, is well-demonstrated in both postmortem human brain studies of major depressive disorder (MDD) patients and animal models of depression." (PMID 36429060, 2022). "In vitro neuronal studies and in vivo models of CUMS revealed that miR-182 directly inhibits BDNF and leads to lower CREB levels and depression-like behaviors." (PMID 35916975, 2022). "A recent study proposed that anthocyanins ameliorate depression-like behavior in CUMS rats by increasing the levels of monoamine neurotransmitters, upregulating BDNF expression, and inhibiting MAOA, which promotes neurogenesis." (PMID 36014776, 2022). "It is reported that Mg supplementation augments serum BDNF in patients with depression, and the addition of Mg pidolate (5 mM) to a co-culture model of BBB/cerebral organoids increases the expression of BDNF." (PMID 36613667, 2022). "Also, omega‐3 may provide xiolytic effects, possibly because it regulates anti‐inflammatory factors, which, in turn, increase brain‐derived neurotrophic factor (BDNF), thereby stimulating the synaptic growth of 5‐hydroxytryptaminergic neurons to reduce anxiety or depression." (PMID 37786585, 2022). "Multiple lines of evidence suggest that brain-derived neurotrophic factor (BDNF) and its receptor tropomyosin receptor kinase B (TrkB) play a crucial role in depression and in the therapeutic mechanisms of antidepressants." (PMID 33963284, 2022). "IL-4-driven Arg1+ microglia in the hippocampus trigger brain-derived neurotrophic factor (BDNF)-driven neurogenesis in reaction to stress, resulting in improved resilience to stress-induced depression." (PMID 36614020, 2022). "Thus, BDNF may be important in the pathology of mental suffering like depression." (PMID 35114967, 2022). "It is suggested that PEA restores dendritic spine number in the hippocampus in the cortisol-induced depression mouse model by the TAAR1 activation and consequent initiation of BDNF/TrkB/CREB signaling." (PMID 35681508, 2022). "Patients with major depressive disorders show low serum BDNF concentrations, while their serum proBDNF concentrations are high." (PMID 36091357, 2022). "Hesperidin efficiently exerted neuroprotective effects in depression and reduced chronic unpredictable mild stress (CUMS) in depressed mice via the NF-κB and BDNF/TrkB pathways." (PMID 36499295, 2022). "Some of the common down genes in maternal C57 mice and depression were for the MAP kinase pathway and some of the common down genes included: FOS, EGR1, DUSP1, BDNF, NR4A1, NR3C1, the neuropeptide somatostatin (SST), and one of the its receptors, SSTR2." (PMID 34997033, 2022).
depression (continued). "At the same time, the CREB/BDNF pathway is significantly decreased in the SNI rats with comorbid anxiety and depression." (PMID 35401106, 2022). "Levels of BDNF and neurotransmitters in the hippocampus were assessed to determine the effect of TTWC in the treatment of depression." (PMID 35237160, 2022). "To research the influence of Hyp on the depression-like behavior of mice mediated by the NLRP1 inflammasome, we detected the mRNA levels of CXCL1, CXCR2, and BDNF in the hippocampus of mice." (PMID 36556951, 2022). "Calcitriol in parental form piles up VDR and brain-derived neurotrophic factor (BDNF) in hippocampus of brain, which clearly proves healing of depression and motor malfunction." (PMID 35669409, 2022). "Given the characterized depression, cognition and memory lesions in PMDD patients, melatonin regulates PMS via BDNF-related pathways." (PMID 36699021, 2022). "Moreover, low BDNF circulating levels have also been reported in other chronic mental disorders, including obsessive-compulsive disorder, major depression, bipolar disorder, and schizophrenia, reasonably pointing to BDNF as a potential biomarker of increased vulnerability also in AN." (PMID 36570702, 2022). "DEX exposure increased anxiety‐ and depression‐like behaviors and plasma CORT levels, while simultaneous OT treatment blocked the adverse effects of DEX, and upregulated p‐CREB and BDNF levels in the dorsal and ventral hippocampus." (PMID 35730145, 2022). "Lithium-induced pharmacological effects were explained by replenishment with BDNF and NGF in patients with depression." (PMID 35892326, 2022). "In summary, the depression model was constructed by intraperitoneal injection of LPS, which activated the ACC and the CREB/BDNF pathway in the ACC." (PMID 35401106, 2022). "Four major hallmarks of the pathophysiology of major depressive disorders (MDDs) are central dopamine levels, inflammation, stress responses via the HPA axis and the autonomic nervous system, and dysfunction of BDNF." (PMID 35631252, 2022). "The result indicated that SIRT1 regulated depression-like behavior by regulating the BDNF expression, and SIRT1 controlled the S-ketamine-evoked release of BDNF in the mPFC of mice, providing a new explanatory mechanism for S-ketamine antidepressant." (PMID 35664490, 2022). "MBCT combined with pharmacotherapy contributes to improve patients' psychological state and compliance and increases the serum levels of BDNF and NGF preventing the recurrence of depression." (PMID 35069013, 2022). "For example, in adult humans, BDNF (brain-derived neurotrophic factor) expression is decreased in the hippocampus and PFC upon exposure to stress and depression, and antidepressant treatment up-regulates BDNF expression." (PMID 35370823, 2022). "Brain-derived neurotrophic factor (BDNF), as the most widely distributed and widely studied neurotrophic factor in the mammalian brain, plays a key role in depression and the mechanisms of action for antidepressants." (PMID 36291673, 2022). "We also showed that overexpressing BDNF in the hippocampus or treating the mice with 7,8-DHF or the anti-inflammatory drug aspirin alleviated depression-like behaviors." (PMID 36578534, 2022). "In the current study, the serum levels of BDNF and CRH with respect to depression and anxiety scores in vitiligo patients and control subjects were compared." (PMID 35508633, 2022). "Brain-derived neurotrophic factor (BDNF) is known to play a critical role in the pathophysiology of many psychiatric disorders, including depression." (PMID 35875661, 2022). "Brain-derived neurotrophic factor (BDNF) in the hippocampus and prefrontal cortex, which is closely related to depressive symptoms, was significantly reduced in patients with depression." (PMID 36297505, 2022). "NYT mititgated the decrease in hippocampal BDNF in COPD mice, and this result is important to clarify the mechanism of improving anxiety and depression." (PMID 36299904, 2022).
depression (continued). "Furthermore, depression and stress enhance the levels of a negative regulator of ERK signaling, MAPK phosphatase-1, which causes depressive behaviors and reduces the levels of the downstream target of BDNF, which is necessary for normal antidepressant activity." (PMID 36499295, 2022). "In this study, BDNF+/−, IDO1−/−, and chronic ultra-mild stress (CUMS)-induced depression mouse models and controls were developed, and the differentially expressed genes were analyzed." (PMID 35711916, 2022). "The inhibition of CREB/BDNF in the anterior cingulate cortex (ACC) reversed pain sensitivity and anxiety–depression behavior induced by peripheral nerve injury." (PMID 36051440, 2022). "In the hippocampus of the animal model of depression, LG upregulated the concentrations of 5-hydroxytryptamine (serotonin; 5-HT) and norepinephrine (NE) and acted on the PI3K/Akt/mTOR-mediated BDNF/TrkB pathway in the hippocampus." (PMID 35323721, 2022). "Results of ELISA revealed that the serum levels of BDNF and NGF were remarkably increased in patients with depression after MBCT (P < 0.001)." (PMID 35069013, 2022). "In most of the top models, a consistent dysregulation of MAP kinase pathway was identified and the genes NR4A1, BDNF, ARC, EGR2, and PDE7B were consistently downregulated as in humans with depression." (PMID 34997033, 2022). "Depression also shows a decrease in GFAP immunoreactivity in the dentate gyrus, which was related to a decrease in BDNF expression." (PMID 35625676, 2022). "Another study showed that resveratrol markedly increases brain derived neurotrophic factor (BDNF) expression in the hippocampus, and this can help to improve depression and anxiety symptoms." (PMID 36120376, 2022). "The aim of our study was to investigate serum brain-derived neurotrophic factor (BDNF) and corticotropin releasing hormone (CRH) levels in vitiligo patients and healthy controls in relation to the observed symptoms of depression and anxiety disorders." (PMID 35508633, 2022). "Butyrate also increases the concentration of the central neurotransmitter 5-HT, promotes the expression of brain-derived neurotrophic factor (BDNF), and significantly improves depression-like behavior in CUMS model mice." (PMID 36290409, 2022). "PF can reverse depression-like behaviors induced by CUMS and PF treatment prevents the reduction in dendritic spine density the expression of BDNF and postsynaptic density protein 95 (PSD95) in the hippocampus of these mice." (PMID 36844911, 2022). "Additionally, PAI-1 may also cause depression by a mechanism independent of tPA and BDNF pathway but associated with impaired serotonin and dopamine metabolism." (PMID 35462923, 2022). "Brain derived neurotrophic factors (BDNF); Chamomile; C-reactive protein (CRP); Depression; Patient health questionnaires 9 (PHQ-9); Saffron; Tryptophan (TRP)." (PMID 36217471, 2022). "Echinacoside ameliorates depression-like behavior in CUMS mice, possibly through enhancing BDNF-CREB pathway and inhibiting neuroinflammation via regulating microglia M1/M2 polarization and JAK1/STAT3 pathway." (PMID 36686689, 2022). "Baseline and 12-weeks follow-up assessment consisted of the Beck Depression Inventory-II (BDI-II) for depression, blood sample for BDNF, respectively the short-Form-36 (SF-36) version 1.0 and disease-specific QoL for QoL." (PMID 36286280, 2022). "Conversely, acute FS induced a significant increase in the levels of both, BDNF and trkB only in the VTA and Acb core of RHA rats which are resilient to stress-induced depression-like behavior." (PMID 36499323, 2022). "After MBCT, the serum levels of BDNF and NGF in patients with depression were 88.47 ± 23.65 (ng/mL) and 93.29 ± 22.62 (ng/mL), respectively." (PMID 35069013, 2022). "C. butyricum has a prominent antidepressant effect, and it significantly improved CUMS-induced depression-like behavior in mice by increasing 5-HT, GLP-1 (glucagon-like peptide-1), and BDNF expression." (PMID 36499295, 2022).
depression (continued). "Evidence suggests that Brain-Derived Neurotrophic Factor (BDNF), a protein known to be involved in brain plasticity mechanisms, can play a key role in both the clinical efficacy of ECT and the pathophysiology of depressive disorders." (PMID 35203890, 2022). "In this regard, BDNF levels are decreased in the post-mortem PFC samples from depressed patients, and in the PFC and hippocampus of rodent models of depression exposed to different types of stress." (PMID 34445375, 2021). "However, the BDNF translational machinery in depression remains unknown." (PMID 32203159, 2021). "Brain-derived neurotrophic factor (BDNF) is known to be involved in the pathogenesis of many disorders of the nervous system, including aggression and depression." (PMID 34769417, 2021). "Modern fast-acting antidepressants used in treatment-resistant depression (TRD), such as esketamine, also increase signaling by neurotrophic factors, e.g., BDNF, influencing neurogenesis." (PMID 33804468, 2021). "NH125 treatment reduced the phosphorylation levels of eEF2 and mTOR, while enhanced BDNF and eventually SNAP25 and PSD95 expression, suggesting an etiological role of eEF2 in LPS-induced synaptogenetic dysfunction and depression." (PMID 33526073, 2021). "The in vivo study suggested RES003 can ameliorate chronic stress induced depression-like behaviours through inhibition of PDE4 and activation of pCREB/BDNF signalling pathway." (PMID 33847209, 2021). "Pde2a inhibitor had significant neuroprotective effects on depression by affecting the cGMP and cAMP signalling pathways, contain increasing the ratio of the expression of pCREB/CREB and BDNF." (PMID 35111057, 2021). "Of these, much research has specifically focused on the role of brain-derived neurotrophic factor (BDNF) and its role in neuroplasticity, neurogenesis and depression." (PMID 33967944, 2021). "Overall, these neurochemical results suggest that SY upregulates the expression of BDNF/TrkB and the PI3K/Akt/mTOR signaling pathway to ameliorate CUMS-induced depression-like symptoms in rats." (PMID 33584387, 2021). "One novel intervention for resistant depression is ketamine, a dissociative that acts as an antagonist of N-Methyl-D-Aspartate (NMDA), and also able to increase plasmatic BDNF levels." (PMID 33921484, 2021). "Thus, BDNF may represent a link between depression and T2DM." (PMID 33506043, 2021). "Similar to other reports, we found that SY significantly improves depression-like symptoms and reduces CUMS-induced BDNF expression." (PMID 33584387, 2021). "Brain-derived neurotrophic factor (BDNF) is the most prominent neurotrophic factor which shows decreased expression and function with depression and reveals an improvement by the antidepressant therapy." (PMID 34630092, 2021). "Molecular mediators, such as glutamate and brain-derived neurotrophic factor (BDNF), have been identified as potential mediators of the bidirectional relationship between T2DM and depression." (PMID 33672126, 2021). "Our data show that P. histicola significantly mitigates depression of OVX mice through improvement in intestinal microbiota to repair intestinal leakage and inhibit central inflammation to promote the expression of BDNF for hippocampal neurogenesis." (PMID 35155523, 2021). "Animal studies have shown that the increase in miR-132 expression negatively correlated with brain-derived neurotrophic factor (BDNF) expression and that inhibiting miR-132 leads to an increase in BDNF expression and to the reduction of depression symptoms." (PMID 34685444, 2021). "These few studies, implicating the roles of synaptic plasticity candidate genes BDNF and CREB1, as well as serotonin receptor gene HTR2A and folate pathway gene MTHFD1L, have exclusively focused on depression as a relevant disorder, or on depressive symptoms." (PMID 34577549, 2021).